BCL2 (BCL2 apoptosis regulator)
Diseases named in the same sentence as BCL2 in open-access papers (continued):
Sharing a sentence is not in itself a finding about the gene and the disease.
cancer (continued). "Resveratrol has an anti-cancer property via an antioxidant defense mechanism which impairs the hydroperoxidase level, matrix metalloproteinase level (MMP-9), Akt signaling pathway, NF-KB pathway, cycloxygenase pathway, protein kinase C, Bcl-2 level and focal adhesion kinase." (PMID 36233012, 2022). "Since BCL2 inhibitors could occupy BH2 and BH3 positions and on the other hand according to our molecular docking analysis, carvacrol and thymol could interact with BCL2 in BH3 and BH1 positions, they may inhibit BCL2 to lead cancer cells to apoptosis pathway." (PMID 35879400, 2022). "Inactivation of FOXM1, an important protein in cancer development and chemoresistance, as part of a FOXM1-AKT-positive regulation circuit, effectively sensitizes venetoclax-resistant AML cells, also making FOXM1 an interesting therapeutic target to combine with targeting BCL-2." (PMID 35884517, 2022). "−Aqueous extract from leaves and seeds had anti-proliferative and pro-apoptotic effects only on cancer cells (not on peripheral blood mononuclear cells—PBMCs).−Pro-apoptotic effect seen with aqueous extract is related with decreased BCL2 levels and sirtuin-1 (SIRT1) protein expression." (PMID 35956938, 2022). "In the current study, we presented recent information on the molecular mechanisms of the Bax/Bcl-2 cascade-mediated EGFR pathway in NSCLC and its therapeutic implications along with clinical investigations that facilitate the treatment and management of several cancers, including NSCLC." (PMID 35402265, 2022). "It has been demonstrated that phloretin and phloretin nanoparticles (PhNPs) induce apoptosis in cancer cell lines via the upregulation of BAX, cytochrome c, PARP, caspases 3 and 9, apoptotic activating factor (APAF) and by downregulating the expression of Bcl-2." (PMID 36557950, 2022). "In order to better understand how variation in cancer cell populations can affect TRAIL sensitization via increased intracellular calcium concentrations, heterogeneous cell populations were simulated by running the model with randomly distributed cytosolic Bcl-2 and XIAP concentrations." (PMID 36080197, 2022). "In addition to Bcl-2, AMPK and Akt are proliferative proteins related to the oncogenic signaling pathway in the progression of cancer and are potential therapeutic targets for cancer treatment." (PMID 33807853, 2021). "Thus, the bioactive compounds from FA and their interactions with PTGS2, HSP90, CDK6, caspase 3, Bcl-2, and MMP9 may be key in the treatment of cardiovascular disease and various cancers." (PMID 33542744, 2021). "In conclusion, targeting all pro-survival Bcl-2 proteins might not offer sufficient selectivity for cancer cells to provide a therapeutic outcome." (PMID 33799470, 2021). "Levels of BCL-2 are also generally decreased following BETi treatment, though notably, other pro-survival proteins including BCL-XL, MCL-1 and BFL-1 have been shown to be reduced in different cancer types, leading to a further reduction in the apoptotic threshold of the cell." (PMID 33799592, 2021). "Six overexpressed oncogenes including BCL2, NOTCH1, SOX4, and CTNNB1 and 10 downregulated tumor suppressor genes including PRKCB, IRF1, CYLD, and TGFB1 were identified as the targets of the DE miRNAs, which may promote cancer development." (PMID 34336826, 2021).
cancer (continued). "It is intriguing that the apoptosis inhibitor BCL2 is among the target genes of YAP1, a fact that could contribute to YAP1 dependency in 20q11.21 amplified cancers, given that the related BCL2L1 protein is dysregulated in these cancers." (PMID 34577783, 2021). "The anti-cancer effect of lycopene was also observed in pancreatic cancer cells (PANC-1 cell line) whereby significant reduction of ROS, NF-κB and anti-apoptotic biomarkers (cIAP1, cIAP2 and survivin) was detected while an increment of caspase-3 and Bax:Bcl-2 ratio was noticed." (PMID 34202203, 2021). "Despite the importance of the connection between deregulated MYC and BCL-2 pro-survival protein expression, and that the mechanisms by which they co-operate in cancer have been known for over two decades, there are still no clinically approved co-treatments that target both proteins." (PMID 33799592, 2021). "D2O-induction of apoptosis has been documented before in a variety of cultured cancer cell lines, involving modulation of apoptotic executioners (such as BAX and BCL2) and markers (including PARP-1 cleavage) through unknown upstream mechanisms responsive to D2O exposure." (PMID 33546433, 2021). "It has been very well established that the B-cell lymphoma 2 (BCL-2) family, including BCL-2, BCL-xL and myeloid cell leukemia 1, are involved in cell death control and apoptosis pathways as well as resistance to traditional chemotherapy agents in many cancers." (PMID 36046114, 2021). "Therefore, the influence of HI 5 on Bcl-2 and Bax expression levels in MCF-7 cancer cells was quantified to ascertain whether HI 5 induces cytotoxicity via the mitochondrial permeability transition pore opening." (PMID 33466812, 2021). "Very interestingly, E.A./CDDP combination completely blunted Bok expression in the cancer cells treated, suggesting that this Bcl-2 ovarian killer, which controlled a non-canonical apoptosis pathway, is not involved in the death process-induced by the combination." (PMID 32033130, 2020). "Anti-apoptotic inhibitors such as A-1331852 (BCL-xL selective), ABT-199 (BCL-2 selective), S63845 (MCL-1 selective) among others that are now evaluated in the clinic, can be used as single agents or especially in combination with other therapies to enhance cancer elimination." (PMID 32801295, 2020). "In this work, Dox would be responsible for inducing cancer cell death by inducing apoptosis, while the used Bcl-2 siRNA would act as a suppressor of cellular antiapoptotic defense (the Bcl-2 protein is the main player for non-pump cancer chemotherapy resistance)." (PMID 32521800, 2020). "In cancer, it is often constitutively activated and able to induce survival and promote cancer progression through the activation of genes coding for proteins that regulate the progression of the cell cycle (e.g., Ciclina D, c-myc) and apoptosis (e.g., CIAP, A1/BFL1, Bcl2, c-Flip)." (PMID 32283655, 2020). "Therefore, the significant increase of Bax/Bcl‐2, and the significant reduction in p‐AKT/AKT and TLR4/NF‐κB indicated that combined treatment with Abx and DSF/Cu2+ significantly attenuates inflammatory effects and promoted the apoptosis of cancer cells." (PMID 32750218, 2020).
cancer (continued). "Therefore, the insufficiency of miR-124-3p inversely correlated with CRKL upregulation might contribute to HCC clinical progression via elevated malignancy of HCC cancer cells through C-JUN, BAX, and BCL-2 deregulations." (PMID 33094104, 2020). "Interestingly, anthracyclines have been reported to provoke Mcl-1 downregulation and thereby synergizing with ABT-263, a non-selective Bcl-2/Bcl-xL inhibitor to kill cancer cells." (PMID 32943617, 2020). "Ongoing clinical trials with ASOs targeting Bcl-2 (NCT04072458), Grb2 (NCT04196257), and androgen receptor (AR; NCT03300505) as well as future mRNA and non-coding RNA targets for the treatment of various solid tumors will in time tell of the efficacy of ASOs for cancer treatment." (PMID 32373584, 2020). "However, if cancer cells have already reached some degree of resistance, the inhibition of mTOR can also generate JNK activation, P-ERK upregulation, and Bcl-2/Bcl-xL phosphorylation in the breast, gastric and esophageal cancer, with subsequent activation of protective autophagy." (PMID 33194736, 2020). "However, the influence of lncRNA on the regulation of oncogenic Bcl-2 in cancer stem cells has not been explored." (PMID 33149126, 2020). "In previous studies, BCL2 protein was not detectable in dormant primordial follicles and primary follicles, leaving the resting reserve in postnatal ovary from individuals not undergoing a cancer situation." (PMID 30857552, 2019). "However, it was also suggested that urocortin may have a dual role in cancer, since it differentially binds to CRFR1 or CRFR2 and either activates or blocks the Bcl-2/Bax/caspase-9 axis, leading to apoptosis or survival, respectively." (PMID 31238876, 2019). "However, no significant change of bcl-2 level was observed in these cell lines, indicating that induction of apoptosis by CuC in different cancer types is mediated through different pathways." (PMID 31780930, 2019). "Moreover, this compound is able to induce cell death in cancer cells that do not express Bcl-2, showing the existence of a Bcl-2-independent mechanism." (PMID 31888223, 2019). "Other mechanisms of successful cancer treatment include overcoming blockades to cancer cell apoptosis by inhibiting the Bcl-2 anti-apoptotic family, whose activity is, not surprisingly, mediated by intracellular (ic) alkalinization (IA) and inhibited by intracellular (ic)acidification (IAc)." (PMID 31480530, 2019). "In addition, NF-kB signaling, one of the major pathways known to be constitutively activated in many cancers was found to be inhibited by GS in HCT 116 cells from the current study, as lowered expression of Bcl-2, cIAP-1, and survivin (the NF-kB target genes) were observed with GS treatment." (PMID 31581454, 2019).
cancer (continued). "Further determination of the apoptotic induction showed that MA or HCD and TMX combination inhibited MDA-MB-231 and MCF-7 cancer cells by upregulating Bax and by downregulating Bcl-2 mRNA and protein expression without altering Caspase-8 and Caspase-12 expression." (PMID 30082655, 2018). "The overexpression of BCL-2 protein is present in over half of all cancers, regardless of type." (PMID 29393886, 2018). "Therefore, it is not surprising that increased expression of pro-survival BCL-2 proteins is found in many cancer types." (PMID 29769323, 2018). "According to previous studies in cancer (MCF-7) cells EGCG up-regulates the expression of miR-16, a member of the miR-15b family (family of miR-16/miR-15a/miR-497/miR-322/miR-195) and consequently, EGCG down-regulates Bcl-2 expression level and thus counteracts cancer progression." (PMID 29163766, 2017). "In addition to BCL2 and BCL‐XL, MCL1 is an important target for cancer therapy." (PMID 28548464, 2017). "Bcl-2 and mTOR are well-known negative regulators of both apoptosis and autophagy while recent evidence indicate that the anti-apoptotic molecule, survivin, also plays a negative modulatory role in autophagy in cancer cells." (PMID 29326587, 2017). "ATO and radiation had a synergistic apoptotic effect on GBM cells by up-regulation of caspase-3 and alteration of the Bax-Bcl-2 balance; therefore, ATO may act as a potential anti-cancer agent against GBM cells through triggering the mitochondrial pathway of apoptosis." (PMID 28459147, 2017). "Here we used two oncogenes, c-MYC and BCL-2, as examples of co-localization of non-B DNA-forming sequences with genetic instability hotspots, because they are commonly involved in chromosomal translocations and the breakpoints in human cancer characterized." (PMID 27532010, 2016). "Oncogenic and apoptotic pathways are exploited towards establishing novel as well as efficient anti-cancer treatment protocols, which involve either Birinapant or AT-406 as single agents or their rational combinations with TRAIL, BRAF600E targeting drugs, and BCL-2 inhibitors." (PMID 27520705, 2016). "However, beginning in the late 1990s, researchers have reported that the functions of Bcl-2 proteins are not confined to cell death control, and at least some Bcl-2 proteins can also regulate cell migration, invasion, and cancer metastasis." (PMID 26621844, 2016). "Targeting apoptosis for the treatment of cancer has become an increasingly attractive strategy, with agents in development to trigger extrinsic apoptosis via TRAIL signalling, or to prevent the anti-apoptotic activity of BCL-2 proteins or inhibitor of apoptosis (IAP) proteins." (PMID 27140313, 2016). "Finally, we demonstrated that psychiatric disorders may share the same signaling pathways with cancers, involving ESR1, BCL2 and MAPK3." (PMID 27917343, 2016). "The ability of HuR-FNP to reduce Bcl2, an anti-apoptotic protein that has been shown to play a key role in cell survival and contribute to resistance against cytotoxics, provides new opportunity for testing HuR-FNP efficacy in Bcl-2 overexpressing drug-resistant cancer cells." (PMID 27328938, 2016). "Expression of the designed inhibitors in human cancer cell lines revealed unique dependencies on BCL2 proteins for survival which could not be inferred from other BCL2 profiling methods." (PMID 27805565, 2016).
cancer (continued). "In view of this, we speculate that the effect of MRC-5-CM on cancer cell apoptosis is mediated partly through regulation of the Bcl-2 gene family, but these genes may not play an essential role." (PMID 26198300, 2015). "Preliminary in vitro experiments confirm that UDCA can induce cancer cell apoptosis by promoting caspase-3, caspase-8, caspase-9, Bax, Fas/FasL, TRAIL, DR4, DR5 and IκB-α gene expression in cancer cells, and reduce the expression of Bcl-2, Bcl-xL, XIAP, cIAP-1, cIAP-2, survivin and NF-κB." (PMID 25951128, 2015). "Bcl-2 is an oncoprotein that function by promoting cancer cell survival rather than proliferation." (PMID 26416353, 2015). "Since cancer types with BCL2 and MCL1 amplification are more prone to inhibition of these proteins, we reasoned that significant frequency of BCL2L1 amplification in a particular cancer type may indicate dependency on BCL-XL for survival." (PMID 26134786, 2015). "Indeed we found that SDE-genes identified in previous step are related to STAT3 pathways including genes involved in cell cycle progression (Cyclin D1, D2, and c-Myc), cell survival (Bcl-xL, Bcl-2, Mcl-1), angiogenesis (HIF1α, VEGF), cancer inflammation (NF-KB, IL-6)." (PMID 26056083, 2015). "In fact, the ratio between Bcl-2, caspase-3 and -8 may be used to determine whether cancer cells are undergoing apoptosis or not." (PMID 25672487, 2015). "Recently, the use of ER stress inducers, like DMC, have raised great interest as potential anti-cancer agents and sensitizers for TRAIL-based therapies, since ER stress was reported to down-regulate important anti-apoptotic proteins, including c-Flip, Bcl-2 and survivin." (PMID 26331107, 2014). "Also, there are accumulating evidences that overexpression of cell survival or anti-apoptotic proteins such as Bcl-2, and Bcl-xL contributes to TRAIL resistance in cancer cells and TRAIL induces apoptosis by binding to its cell surface death receptors such as DR4 and DR5." (PMID 25015549, 2014). "Although most HPV 16 is not directly involved in Bcl-2 activation, it is clear that there is a connection between E6 and Bcl-2 expression, which could play a direct role in cancer development." (PMID 25699089, 2014). "Our findings, pointing a role of Bcl-2/Baxexpression ratio in the progression of TCC,indicate that this ratio may be used as a significantprognostic indicator for prediction ofthe clinical outcome for patients with lowgradebladder cancer." (PMID 24381861, 2014). "Notably, Mcl-1 is responsible for the resistance to the new generation of BH3 mimetic cancer therapies, including ABT-737 and ABT-263, which bind to the anti-apoptotic proteins Bcl-2, Bcl-xL and Bcl-w to disrupt their interaction with the pro-apoptotic Bcl-2 family members." (PMID 24814761, 2014). "Unlike cancer cells, there is a lack of direct evidence supporting the connection between the anti-atherogenic effect of luteolin and apoptosis signaling pathways, such as Bcl-2, Bax, Caspase and its role in VSMCs." (PMID 23686014, 2013). "The first group consists of cancer cells whose drug resistance can be overcome by exposing the cells to GCs in combination with drugs that target protein kinases such as Akt, mTOR, Src, ALK, and/or BCR, or drugs antagonizing Bcl-2, Bcl-XL, Mcl-1, c-Myc, or Notch." (PMID 23431463, 2013).